GOT2 (glutamic-oxaloacetic transaminase 2)
Description:
Catalyzes the irreversible transamination of the L-tryptophan metabolite L-kynurenine to form kynurenic acid (KA). As a member of the malate-aspartate shuttle, it has a key role in the intracellular NAD(H) redox balance. Is important for metabolite exchange between mitochondria and cytosol, and for amino acid metabolism. Facilitates cellular uptake of long-chain free fatty acids.
Synonyms: mAspAT; KYAT4; mitAAT; KATIV; KAT4; DEE82
Tractability: Antibody: UniProt places it where antibodies can reach, with high confidence; its Gene Ontology location is reachable by antibodies, with high confidence. PROTAC: ubiquitination databases record sites on it; its protein half-life has been measured.
Target class: Enzyme; Transferase
Gene: Protein-coding gene on chromosome 16 (58,707,130 to 58,734,361, reverse strand). Ensembl gene ENSG00000125166.
Subcellular location: Mitochondrion matrix; Cell membrane
Pathways (Reactome):
Metabolism: Aspartate and asparagine metabolism; Degradation of cysteine and homocysteine; Glutamate and glutamine metabolism; Glyoxylate metabolism and glycine degradation; Malate-aspartate shuttle
Gene Ontology:
Molecular function: L-aspartate:2-oxoglutarate aminotransferase activity; RNA binding; catalytic activity; kynurenine-oxoglutarate transaminase activity; pyridoxal phosphate binding; transaminase activity
Biological process: fatty acid transport; L-aspartate catabolic process; malate-aspartate shuttle; response to ethanol; 2-oxoglutarate metabolic process; aspartate metabolic process; glutamate metabolic process; trans-4-hydroxy-L-proline catabolic process; amino acid metabolic process; L-asparagine biosynthetic process; L-glutamine catabolic process
Cellular component: extracellular exosome; mitochondrion; plasma membrane; mitochondrial matrix
Genetic constraint (gnomAD): Loss-of-function variants: 17 observed, 43.13 expected, observed/expected ratio (o/e) 0.39, 90% interval 0.27 to 0.59. The upper end of that interval is the gene's LOEUF score, 0.59, which puts it in group 2 of 6, group 1 being the genes least tolerant of losing a copy. Missense variants: 407 observed, 515.44 expected, observed/expected ratio (o/e) 0.79, 90% interval 0.73 to 0.86. Synonymous variants: 161 observed, 185.39 expected, observed/expected ratio (o/e) 0.87, 90% interval 0.76 to 0.99.
Gene-disease validity (ClinGen):
ClinGen rates the evidence that GOT2 causes each of these diseases.
mitochondrial disease (autosomal recessive): Moderate.
Homologues: Orthologues: chimpanzee GOT2 (99% identical), macaque GOT2 (99% identical), mouse Got2 (95% identical), rat Got2 (95% identical), guinea pig GOT2 (93% identical), pig GOT2 (88% identical), dog GOT2 (87% identical), tropical clawed frog got2 (82% identical), zebrafish got2a (79% identical), zebrafish got2b (77% identical), Caenorhabditis elegans got-2.2 (66% identical), rat Got2-ps6 (65% identical), and 2 more. Paralogues in human: GOT1 (47% identical), GOT1L1 (28% identical).
Diseases named in the same sentence as GOT2 in open-access papers:
GOT2 is named in the same sentence as 177 diseases in open-access papers, as found by Europe PMC text mining. Sharing a sentence is not in itself a finding about the gene and the disease. The quoted sentences say what the papers report.
pancreatic cancer (21 papers, 2018 to 2025). "In pancreatic cancer, loss of GOT2 causes dysfunction of the malate-aspartate shuttle and subsequently disrupts cellular redox homeostasis while impairing both the TCA cycle and glycolysis." (PMID 41299514, 2025). "Given that pancreatic cancer exhibits a unique GOT2-dependent glutamine metabolism, there must be other compensatory metabolic pathways for pancreatic cancer cells in vivo to survive under GOT2-deficient conditions." (PMID 40247913, 2025). "CAFs conditioned medium can rescue the proliferation of GOT2-deficient pancreatic cancer cells in vitro, while inhibiting pyruvate uptake and metabolism can block their recovery." (PMID 40247913, 2025). "CAFs indirectly compensate for the insufficient Asp due to GOT2 deficiency by releasing the redox-active metabolite pyruvate to GOT2-deficient pancreatic cancer cells." (PMID 40247913, 2025). "Pancreatic cancer-associated fibroblasts (CAFs) release pyruvate and compensate for loss of glutamate-oxaloacetate transaminase 2 (GOT2) in vitro." (PMID 35815941, 2022). "Clinically, regulation of GOT2 has been linked to suppression of pancreatic cancer cell growth." (PMID 37839702, 2023). "Glutamate oxaloacetate transaminase 2 (GOT2) has been repeatedly reported in recent years to be associated with the progression of pancreatic cancer, but its role in HCC remains unclear." (PMID 33300278, 2021). "In pancreatic cancer, which is characterized by activating mutations in K-Ras in more than 90% of cases, mitochondrial glutamate-oxaloacetate transaminase 2 (GOT2) utilizes glutamine-derived glutamate and oxaloacetate (OAA) to generate aspartate that is then exported to cytosol." (PMID 30197878, 2018). "Previous findings demonstrate that upon the knockout of GOT2 using CRISPR/Cas9 technology, pancreatic cancer cells deficient in GOT2 exhibited markedly restricted growth in immunocompetent syngeneic mouse models." (PMID 40422699, 2025). "The study of Abrego and colleagues has revealed the part-time function of the metabolic enzyme GOT2 in pancreatic cancer: the GOT2-PPARδ axis significantly regulates the immune microenvironment of pancreatic cancer to inhibit anti-tumor immunity." (PMID 40247913, 2025). "In pancreatic cancer, GOT2 acetylation promotes its interaction with malate dehydrogenase 2, forming a functional complex that activates MAS to maintain NADH/NAD+ homeostasis, thus driving tumor proliferation." (PMID 40842990, 2025). "Consistent with its conventional metabolic effects, GOT2 knockdown (KD) in cultured pancreatic cancer cells results in decreased Asp and α-KG production, thereby preventing the normal TCA cycle and decreasing ATP levels." (PMID 40247913, 2025). "Enzymes involved in the glutamine metabolic reprogramming (mitochondrial GLS1 (glutaminase 1), GOT1, and GOT2) are highly up-regulated in pancreatic cancer." (PMID 40247913, 2025). "The authors further found that GOT2 was localized in the nucleus in pancreatic cancer cells and acted as a fatty acid-binding protein to regulate the transport of nuclear fatty acids, and bind to and activate PPARδ, promoting its transcriptional activity." (PMID 40247913, 2025). "According to existing research, we have a deeper understanding of the roles of GOT2 in pancreatic cancer, and in addition to its well-known metabolic significance, the unexpected role of immunosuppression also deserves our attention." (PMID 40247913, 2025). "Cellular metabolic reprogramming and intrinsic immune escape are key features of pancreatic cancer, and GOT2, as a metabolic enzyme, bridges organically the two, presenting a broader prospect for targeting GOT2 to treat pancreatic cancer." (PMID 40247913, 2025).
pancreatic cancer (continued). "This prompts us to develop mouse models that more accurately reproduce human disease to fully understand how the metabolic and immune effects of GOT2 interact in pancreatic cancer." (PMID 40247913, 2025). "In this paper, we will elaborate on the metabolic and immune effects of GOT2 in pancreatic cancer based on existing studies, with a view to opening up new avenues for the treatment of pancreatic cancer." (PMID 40247913, 2025). "Low SIRT3 expression level was observed in human pancreatic tumor with increased GOT2 acetylation, and this enhances its interaction with MDH2, thereby promoting the transfer of NADH from cytosol to mitochondria via MAS." (PMID 41299514, 2025). "Currently, studies have demonstrated that GOT2 depletion leads to impaired proliferation and disrupted redox homeostasis in pancreatic cancer cells in vitro." (PMID 40247913, 2025). "Acetylation of GOT2 at the K404 lysine residue promotes the proliferation of pancreatic cancer cells and tumor growth in vivo, and GOT2 acetylation at the lysine residue K159 is increased in human pancreatic tumors." (PMID 36959802, 2023). "This is a physiologically relevant concentration of pyruvate in serum collected from mice harboring pancreatic tumors, and 250 μM pyruvate rescued GOT2 KD in vitro." (PMID 35815941, 2022). "Amino-oxyacetic acid, an inhibitor of GOT1/GOT2 and other transaminases, diminishes oxygen consumption, reduces the growth of breast cancer cells and xenografts, and induces senescence in pancreatic cancer cells." (PMID 35831624, 2022). "We show that cancer-associated fibroblasts (CAFs), a major component of the pancreatic tumor microenvironment (TME), release the redox active metabolite pyruvate, and culturing GOT2 KD cells in CAF conditioned media (CM) rescued proliferation in vitro." (PMID 35815941, 2022). "Small molecule inhibitors of GOT2 are expected to be effective therapeutics for pancreatic cancer." (PMID 40247913, 2025). "This provides new insights into pancreatic cancer treatment and prompts us to consider whether targeting GOT2 to promote immune response could extend beyond pancreatic cancer cells." (PMID 40247913, 2025). "New and more potent autophagy inhibitors are also being developed, which may block pancreatic cancer cells from acquiring Asp via micropinocytosis and hopefully slow the growth of GOT2 KD pancreatic tumors." (PMID 40247913, 2025). "In this paper, we will comprehensively and systematically elaborate on the metabolic and immune functions of GOT2 and the corresponding molecular mechanisms in pancreatic cancer based on existing research, with the aim of providing new ideas and approaches for pancreatic cancer treatment." (PMID 40247913, 2025). "GOT2 can inhibit pancreatic cancer cell senescence by maintaining cellular redox balance." (PMID 40247913, 2025). "Under hypoxic conditions, pancreatic cancer cells depend on GOT2 to synthesize endogenous Asp." (PMID 40247913, 2025). "Given the elevated levels of GOT2 K159 acetylation in pancreatic cancer, this could be a potential biomarker for pancreatic cancer diagnosis." (PMID 40247913, 2025). "Recently, a study has revealed an unexpected nuclear role of GOT2 in pancreatic cancer." (PMID 40247913, 2025). "GOT2 plays a suppressive and promoting role in HCC and pancreatic cancer, respectively, which may be associated with generating glutathione through different pathways to maintain cellular redox balance." (PMID 40247913, 2025). "Finally, because pancreatic cancer patients suffer from severe immunosuppression and dysfunction of T-cell populations, whether targeting GOT2 is sufficient to reverse the immune suppression in this case remains to be investigated." (PMID 40247913, 2025).
pancreatic cancer (continued). "Therefore, it is important to consider the role of tumor microenvironment in metabolic therapies targeting GOT2 in pancreatic cancer and gain a better understanding of its potential resistance mechanisms, which will be beneficial to develop more effective metabolic therapies." (PMID 40247913, 2025). "Thus, SIRT3 may act as a tumor suppressor in pancreatic cancer, and GOT2 deacetylation drugs targeting this need to be explored." (PMID 40247913, 2025). "Here, pyruvate, as an electron acceptor, is transported into pancreatic cancer cells via monocarboxylate transporter 1 (MCT1) and converted to lactate via lactate dehydrogenase (LDH), which can restore the redox imbalance caused by GOT2 deficiency and reverse the GOT1 pathway to synthesize Asp." (PMID 40247913, 2025). "However, these interventions are ineffective against GOT2 KD tumors in vivo, which may indicate the presence of other Asp sources in pancreatic tumor microenvironment." (PMID 40247913, 2025). "However, pancreatic tumors in vivo may use alternative pathways to obtain Asp, thereby bypassing the dependence on GOT2." (PMID 40247913, 2025). "Additionally, GOT2 overexpression could inhibit senescence of pancreatic tumor cells and therefore contribute to tumor progression." (PMID 30714292, 2019). "Moreover, nuclear GOT2 has been shown to promote the transport of fatty acids, such as arachidonic acid, by interacting with peroxisome proliferator-activated receptor δ (PPARδ) and markedly activating the PPARδ signaling pathway in a mouse pancreatic cancer cell line." (PMID 41451371, 2025). "Moreover, recent studies have revealed compensatory mechanisms of pancreatic cancer to bypass GOT2 dependence, which prompts us to target resistance mechanisms for improved treatment and to focus on whether fibroblasts mediate resistance to GOT2 silencing in the intact immune system." (PMID 40247913, 2025). "Therefore, targeting GOT2 may provide sufficient therapeutic window to protect the surrounding tissues from damage and become one of the effective and specific strategies for treating pancreatic cancer." (PMID 40247913, 2025). "SIRT3-dependent glutamic-oxaloacetic transaminase 2 (GOT2) K159Ac status affects malate-aspartate NADH shuttle activity and pancreatic tumor growth." (PMID 39372420, 2024). "GOT2 acetylation is essential for regulating the mitochondrial NADH/NAD+ ratio and stimulating the production of NADPH to maintain the redox state of pancreatic cancer cells." (PMID 36959802, 2023). "Aspartate aminotransferase 2 (GOT2) promotes ATP production and ROS homeostasis, supporting pancreatic tumor growth in vivo." (PMID 35831624, 2022). "Downregulation of glutamic-oxaloacetic transaminase 2 (GOT2) activates oxidative stress in human pancreatic ductal adenocarcinoma (PDAC) cells and inhibits the proliferation of pancreatic cancer." (PMID 34557495, 2021). "elucidated a novel mechanism whereby SIRT3‐dependent GOT2 acetylation affects the malate–aspartate NADH shuttle activity and promotes pancreatic tumor growth." (PMID 30714292, 2019). "Kerk et al19 and Garcia-Bermudez et al21 found that proliferation of pancreatic cancer cells in vitro is dependent on GOT2, but that GOT2 is not required for tumor growth in immunodeficient or immunocompetent mouse xenograft models of pancreatic cancer." (PMID 40247913, 2025). "In addition, SIRT3 (sirtuin-3)-dependent GOT2 acetylation stimulates the malate-aspartate NADH shuttle activity and oxidative protection, thereby promoting pancreatic tumor growth." (PMID 40247913, 2025). "GOT2 knockout did not affect the proliferation of pancreatic cancer cells in vitro and tumor progression in immunocompromised mouse models, but severely impaired xenograft growth in mice with intact immune systems." (PMID 40247913, 2025).
pancreatic cancer (continued). "Additionally, SIRT3 impedes the malate-aspartate shuttle by deacetylating glutamate oxaloacetate transaminase 2 (GOT2), curtailing glycolysis and thus inhibiting the growth of pancreatic tumor cells." (PMID 38773972, 2024). "Consequently, the knockdown of Got2 impairs key cellular metabolic processes (glycolysis and the TCA cycle) while reducing the cellular proliferation of pancreatic cancer cell lines." (PMID 39000422, 2024). "Indeed, GOT2-mediated aspartate production is observed in wild-type cells using the oxidative TCA cycle for aspartate synthesis and in hypoxic pancreatic cancer cells." (PMID 36883551, 2023). "Single-cell transcriptomic analysis further confirmed that GOT2 is widely expressed in non-malignant cells within the pancreatic tumor microenvironment, including macrophages, CD8+ T cells, and endothelial cells, with expression levels positively correlated with metabolic activity." (PMID 40842990, 2025). "SIRT3 has been identified as the main deacetylase of GOT2, and its deacetylation may not affect the enzyme activity of GOT2 itself but impairs the GOT2-MDH2 association, which negatively regulates malate-aspartate shuttle and impairs pancreatic cancer cell proliferation." (PMID 40247913, 2025).
breast carcinoma (17 papers, 2017 to 2025). "Concurrently, elevated GOT2 levels have been linked to the accelerated proliferation of breast cancer cells." (PMID 38915066, 2024). "In breast cancer, sensitivity to a nucleotide synthesis inhibitor, methotrexate, has been linked to high GOT2 expression." (PMID 31968678, 2020). "BRCA1/ZBRK1 repressor complex reduces Asp biosynthesis through transcriptional repression of GOT2 expression, thereby leading to impaired proliferation of breast cancer cells." (PMID 40247913, 2025). "Due to the impairment of this complex, the production of GOT2 increased, which resulted in the rapid proliferation of breast cancer cells." (PMID 37693904, 2023). "The GOT2 gene is repressed by the tumor suppressor BRCA1 in breast cancer cells, and related to poor survival in TNBC patients." (PMID 35831624, 2022). "For further validation, we treated breast cancer cells that were stable ectopic overexpression or knockdown of GOT2 with different concentrations of MTX." (PMID 30714292, 2019). "Collectively, these findings demonstrated the correlation between BRCA1/ZBRK1 and GOT2 in breast cancer samples and suggested the promising prognostic value of GOT2 in clinical practice." (PMID 30714292, 2019). "In summary, our findings reveal that BRCA1 modulates aspartate biosynthesis through transcriptional repression of GOT2, and provides a biological basis for treatment choices in breast cancer." (PMID 30714292, 2019). "We observed that downregulation of GOT2 significantly attenuated, and upregulation of GOT2 promoted, cell proliferation and colony formation of breast cancer cells." (PMID 30714292, 2019). "The results showed that knockdown of GOT2 substantially increased the IC50 of MTX, whereas overexpression of GOT2 reduced the IC50 in breast cancer cells." (PMID 30714292, 2019). "The expression level and activity of the GOT2 enzyme has been found to be highly elevated in pancreatic and breast cancer cells." (PMID 28446878, 2017). "In addition, GOT2 and GLS as prognostic biomarkers for breast cancer, are closely associated with dendritic cells and immunotherapy response." (PMID 40247913, 2025). "In breast cancer, the BRCA1/ZBRK1 complex represses GOT2 promoter activity, suggesting that BRCA1 loss-of-function may upregulate GOT2 by removing this repression." (PMID 40842990, 2025). "Here, we found that GOT2 overexpression sensitized breast cancer cells to MTX." (PMID 30714292, 2019). "Our study also demonstrated that GOT2 was crucial for breast cancer progression and could serve as a predictor of methotrexate (MTX) sensitivity." (PMID 30714292, 2019). "Interestingly, MTX, a classic chemotherapeutic drug for breast cancer treatment, was the top ranked drug positively correlated with GOT2 mRNA level among FDA approved drugs or those under clinical trials." (PMID 30714292, 2019). "Given that aspartate is a critical metabolite for cell proliferation and biomass production, we further asked whether GOT2 could promote the malignant phenotypes of breast cancer cells through mediating aspartate biosynthesis." (PMID 30714292, 2019). "Taken together, our results revealed that GOT2 could partially evoke malignant phenotypes of breast cancer cells via its catalytic function." (PMID 30714292, 2019). "Interestingly, we also demonstrated that GOT2 overexpression sensitized breast cancer cells to methotrexate, suggesting a promising precision therapeutic strategy for breast cancer treatment." (PMID 30714292, 2019). "In breast cancer, high expression of GLS and low expression of glutamate-oxaloacetate transaminase 2 (GOT2) correlate positively with the presence of DCs and suggest an enhanced response to immunotherapy." (PMID 39905317, 2025). "Additionally, the mRNA level of GOT2 was significantly positively correlated with poor OS and DFS of Luminal A or HER2‐positive breast cancer and positively correlated with OS in basal‐like subtype BC." (PMID 30714292, 2019).